ENSG00000264577 (novel transcript, antisense to RPL23A)
Gene: Long non-coding RNA gene on chromosome 17 (28,721,487 to 28,722,877, reverse strand). Ensembl gene ENSG00000264577.
Gene Ontology:
Biological process: RNA processing
Cellular component: nucleolus